LAIR1 (leukocyte associated immunoglobulin like receptor 1)
Description:
Functions as an inhibitory receptor that plays a constitutive negative regulatory role on cytolytic function of natural killer (NK) cells, B-cells and T-cells. Activation by Tyr phosphorylation results in recruitment and activation of the phosphatases PTPN6 and PTPN11. It also reduces the increase of intracellular calcium evoked by B-cell receptor ligation. May also play its inhibitory role independently of SH2-containing phosphatases. Modulates cytokine production in CD4+ T-cells, down-regulating IL2 and IFNG production while inducing secretion of transforming growth factor beta. Also down-regulates IgG and IgE production in B-cells as well as IL8, IL10 and TNF secretion. Inhibits proliferation and induces apoptosis in myeloid leukemia cell lines as well as prevents nuclear translocation of NF-kappa-B p65 subunit/RELA and phosphorylation of I-kappa-B alpha/CHUK in these cells. Inhibits the differentiation of peripheral blood precursors towards dendritic cells.
Synonyms: LAIR-1; CD305
Tractability: Small molecule: a structure with a bound ligand is known. Antibody: UniProt places it where antibodies can reach, with high confidence; its Gene Ontology location is reachable by antibodies, with high confidence; UniProt predicts a signal peptide or a membrane-spanning region; the Human Protein Atlas places it where antibodies can reach. PROTAC: ubiquitination databases record sites on it; its protein half-life has been measured.
Gene: Protein-coding gene on chromosome 19 (54,351,384 to 54,370,558, reverse strand). Ensembl gene ENSG00000167613.
Subcellular location: Cell membrane
Subcellular location (Human Protein Atlas): Plasma membrane
Pathways (Reactome):
Immune System: Immunoregulatory interactions between a Lymphoid and a non-Lymphoid cell; Neutrophil degranulation
Gene Ontology:
Molecular function: protein binding; immune receptor activity; transmembrane signaling receptor activity
Biological process: immune response-inhibiting cell surface receptor signaling pathway
Cellular component: plasma membrane; specific granule membrane; tertiary granule membrane
Genetic constraint (gnomAD): Loss-of-function variants: 24 observed, 32.68 expected, observed/expected ratio (o/e) 0.73, 90% interval 0.53 to 1.03. The upper end of that interval is the gene's LOEUF score, 1.03, which puts it in group 4 of 6, group 1 being the genes least tolerant of losing a copy. Missense variants: 350 observed, 343.56 expected, observed/expected ratio (o/e) 1.02, 90% interval 0.93 to 1.11. Synonymous variants: 150 observed, 140.06 expected, observed/expected ratio (o/e) 1.07, 90% interval 0.94 to 1.23.
Homologues: Orthologues: chimpanzee LAIR1 (97% identical), macaque LAIR1 (77% identical), dog LAIR1 (47% identical), mouse Lair1 (40% identical), rat Lair1 (38% identical).
Diseases named in the same sentence as LAIR1 in open-access papers:
LAIR1 is named in the same sentence as 116 diseases in open-access papers, as found by Europe PMC text mining. Sharing a sentence is not in itself a finding about the gene and the disease. The quoted sentences say what the papers report.
lung carcinoma (14 papers, 2020 to 2026). "In tumors with abundant collagen deposition (e.g., lung cancer), expression of the collagen receptor leukocyte-associated immunoglobulin-like receptor-1 (LAIR1) is significantly upregulated." (PMID 41362727, 2026). "Increased LAIR-1 expression and LAIR-1-dependent CD8+ T-cell exhaustion in lung cancer are induced by the interaction between integrin β1 (CD18) and collagens." (PMID 38946426, 2024). "The widespread expression pattern of LAIR-1 across lung carcinomas especially in NSCLC invokes the need for its study in TME regulation." (PMID 36960400, 2023). "Our results from the NSCLC discovery cohort were validated by single-cell sequencing of three lung carcinomas where LAIR-1 was highly expressed on CK8/CK10+ tumor cells and CD68+ and CD163+ macrophages." (PMID 36960400, 2023). "Recently, it was reported that PD-1 inhibitor–treated patients with increased collagen and LAIR-1 expression exhibit poorer response and survival outcomes in lung cancers." (PMID 36960400, 2023). "This study shows that LAIR-1 is highly expressed in Hodgkin lymphoma, head and neck, testicular, and lung cancer." (PMID 36960400, 2023). "Patient tumor analyses corroborate our preclinical observations and identify collagen and LAIR1 as potential markers of immune suppression in lung cancers." (PMID 32908154, 2020). "Our findings from datasets of melanoma patients treated with anti-PD-1 therapies corroborate our preclinical lung cancer observations and validate collagen and LAIR1 as potential predictive markers of adaptive resistance to immunotherapy." (PMID 32908154, 2020). "Our work identifies collagen and LAIR1 as a potential marker of PD-1/PD-L1 blockade resistance in lung cancer and validates multiple therapeutic targets in combination with immune checkpoint blockade." (PMID 32908154, 2020). "In addition, collagens can promote immunotherapy resistance in lung cancer through LAIR1-dependent CD8+ T cell exhaustion." (PMID 41306970, 2025). "In addition to the high expression of LAIR1 in macrophages, flow cytometry also found that cDCs and pDCs were also highly expressed in cDC and pDC cells in three tumors, and monocytes from colorectal and lung cancers were also found to express LAIR1." (PMID 39120585, 2024). "David and colleagues discovered that collagen binds to LAIR-1 on T cells and activates the src homology region 2 domain–containing phosphatase 1 pathway, thereby inducing a T-cell exhaustion alternative to the PD-1 pathway in lung cancer." (PMID 37529399, 2023). "Lastly, our pre-clinical and clinical findings emphasize the need to develop specific inhibitors of LAIR1 to synergize with PD-1/PD-L1 blockade therapies and emphasize the need to have greater accessibility to lung cancer patient datasets with pre- and post-treatment samples." (PMID 32908154, 2020). "Additionally, one study showed that LAIR-1-deficient mice present exacerbation of disease in lung cancer models, but that LAIR-1 deficiency does not affect subcutaneous tumour growth." (PMID 38236251, 2024). "Our in vivo findings show a promising correlation with the in vitro observations, illustrating that anti-Lair1 antibody extends survival in preclinical models of aggressive tumors, such as GBM and lung cancer, which resist PD-1 blockade." (PMID 40591413, 2025). "The protein expression pattern of LAIR-1 in multitumor TMA (YTMA-395) from 12 different types of solid tumors and hematologic malignancies showed that LAIR-1 is more highly expressed in lung cancer compared with most other tumor types." (PMID 36960400, 2023). "To clarify the effect of lAIR1 blockade on MDSC activity, we treated enriched MDSCs isolated from a lung cancer patient with squamous cell carcinoma with h219-LLG or control antibodies in the presence or absence of collagen." (PMID 36211388, 2022).
lung carcinoma (continued). "We also investigated the involvement of a ColI receptor, Lair1, in CD8+ T cell dysfunction, given a recent report that Lair1 negatively regulates CD8+ T cell activity and may promote immunotherapy resistance in lung cancer." (PMID 38652549, 2024). "The main objective of this study was to investigate LAIR-1 protein expression using quantitative immunofluorescence (QIF) and to assess its prognostic value alone or in combination with PD-L1 in patients with early-stage non–small cell lung cancer (NSCLC)." (PMID 36960400, 2023). "In addition, the introduction of the LAIR-1 decoy protein, LAIR-2, sensitizes previously resistant lung tumors to programmed death-1 (PD-1) blockade, indicating the potential of LAIR-1 as an alternative marker for anti-PD-1 resistance in lung cancer." (PMID 36960400, 2023). "Therefore, mechanistically validating LAIR1 and SHP-1 as additional therapeutic targets in combination with PD-1/PD-L1 blockade is vital to circumvent the need for early LOXL2 inhibition and to allow treatment of lung cancer patients with late-stage disease." (PMID 32908154, 2020).
systemic lupus erythematosus (14 papers, 2014 to 2025). An autoimmune multi-organ disease typically associated with vasculopathy and autoantibody production. "LAIR1 has been associated with the pathogenesis of several autoimmune diseases, including systemic lupus erythematosus (SLE), rheumatoid arthritis (RA), allergy (airway hyper-reactivity and asthma), graft rejection (kidney transplant), and chronic hepatitis." (PMID 41153806, 2025). "Defective expressions of LAIR-1 on both B cells and plasmacitoid dendritic cells have previously been found in lupus patients, and such defective expressions can result in a lower inhibiting signal in Ig production after LAIR-1 and collagen interaction." (PMID 31597242, 2019). "The role of LAIR-1 in chronic inflammatory processes, such as rheumatoid arthritis and systemic lupus erythematosus, suggest that LAIR-1, as an inhibitory receptor, may contribute to the pathophysiology of post-chronic inflammation, including post-HCV." (PMID 36293412, 2022). "Emerging research suggests that targeting the interactions between C1q and LAIR-1 could enable the development of new treatments for many diseases, including inflammatory diseases, the autoimmune condition lupus, a variety of cancers, and possibly Covid-19." (PMID 35562585, 2022). "In addition, the expression of inhibitory receptors have been reported to be decreased in DCs from lupus patients such as the expression of LAIR-1 on pDCs of juvenile lupus patients." (PMID 25229821, 2014). "The expression and function of LAIR1 was also analyzed in patients with autoimmune diseases such as systemic lupus erythematosus (SLE), mixed connective tissue disease (MCTD), systemic sclerosis (SSc), and rheumatoid arthritis (RA) patients." (PMID 40563506, 2025). "More recently, it has also been shown in monocytes and pDCs that LAIR1 cross-linking or binding to cognate ligands collagen and C1Q can inhibit the production of IFNα in response to Toll-like receptor ligands in healthy controls and patients with systemic lupus erythematosus." (PMID 34429372, 2021). "Consistent with defective self-tolerance, CD33/LAIR-1 expression is reduced in systemic lupus erythematosus (SLE) myelomonocytes." (PMID 28325905, 2017). "Altered expression of LAIR-1 levels in rheumatoid arthritis (RA) and systemic lupus erythematosus (SLE) patients correlates with inflammation, which indicates a potential role of LAIR-1 in these chronic inflammatory diseases." (PMID 31019980, 2019). "It is also explained the significantly decreased number of LAIR1+ glomerulus/ kidney area in PBS‐treated lupus mice rather than IL‐35p and Treg treatments." (PMID 33634995, 2021).
rheumatoid arthritis (13 papers, 2012 to 2025). A chronic, systemic autoimmune disorder characterized by inflammation in the synovial membranes and articular surfaces. "The other two—LAIR1 and TNFRSF14—appear to be more specifically associated with rheumatoid arthritis." (PMID 39887658, 2025). "In Rheumatoid arthritis citrullinated collagen can bind LAIR-1 as decoy ligand impairing the immunosuppressive function of LAIR-1 on T cells." (PMID 38659022, 2024). "Our different in vitro and in vivo models indicate that inflammation leads to an upregulation of LAIR-1, as observed here in monocytes from sepsis patients, but also on circulating monocytes in acute myocardial infarction, rheumatoid arthritis and liver cirrhosis." (PMID 32973751, 2020). "Moreover, decreased levels of LAIR1 in circulating CD4 T cells in synovial fluid and increased levels of LAIR1 in Mos and local CD68+ macrophages in synovial tissue have been used as biomarkers of active rheumatoid arthritis patients." (PMID 39940787, 2025). "Moreover, soluble LAIR-1, a shed form of LAIR-1, and the soluble family member LAIR-2 are increased in urine and synovial fluid of rheumatoid arthritis patients." (PMID 32973751, 2020). "Taken together, these data show that the effect of vitamin D on inflammation is at least, in part, mediated by LAIR-1 and that non-calcemic 20S(OH)D3 may be a promising therapeutic agent for the treatment of autoimmune diseases such as Rheumatoid Arthritis." (PMID 34948139, 2021). "For comparison, LAIR1 expression was also determined on B lymphocytes from patients suffering from mixed connective tissue disease (MCTD), systemic sclerosis (SSc) and rheumatoid arthritis (RA)." (PMID 22355402, 2012). "LAIR1 expression in peripheral blood B lymphocytes from 54 SLE, 24 mixed connective tissue disease (MCTD), 20 systemic sclerosis (SSc) patients, 14 rheumatoid arthritis (RA) and 40 sex and age matched healthy donors (HD) have been analyzed by immunofluorescence." (PMID 22355402, 2012).
autoimmune disease (12 papers, 2010 to 2025). A disorder resulting from loss of function or tissue destruction of an organ or multiple organs, arising from humoral or cellular immune responses of the individual to their own tissue constituents. "Increased expression of tenascin-C, OPN and TSP-1 is associated with autoimmune diseases, while collagen immunosuppressive receptor LAIR-1 decreases in chronic autoimmune disease." (PMID 33262757, 2020). "As a consequence, LAIR1 appears to play a role in some autoimmune diseases and the immune response against tumor cells." (PMID 40563506, 2025). "Further, more detailed studies in these and other autoimmune diseases should be performed to better define the functional properties of immune subsets expressing LAIR1 to propose this molecule as a therapeutic target." (PMID 40563506, 2025). "LAIR1’s involvement in various cancer types, autoimmune diseases, and infectious diseases has been extensively researched." (PMID 38933531, 2024). "In conclusion, there is clear evidence that LAIR1 represents a very attractive therapeutic target for the treatment of a variety of inflammatory and autoimmune diseases, as well as hematological malignancies." (PMID 36555775, 2022). "We will also discuss potential therapeutic strategies targeting LAIR1 for the treatment of various autoimmune diseases and cancer settings." (PMID 36555775, 2022). "These observed effects motivate future study on the potential of LAIR1-LP and other collagen-mimetic peptides as a therapeutic biomaterial for the treatment of autoimmune diseases." (PMID 32719788, 2020). "In conclusion, LAIR1 engagement by collagen-like domains could be an interesting therapeutic strategy to control inflammation in autoimmune diseases such as RA, SLE, and many other inflammatory states." (PMID 36555775, 2022). "LAIR-1 is also involved in some autoimmune diseases and tumors." (PMID 29915163, 2018). "Thus, LAIR-2 may function as a pro-inflammatory mediator by decreasing the inhibitory potential of the immune inhibitor LAIR-1, resulting in enhanced activation of immune cells, a characteristic of autoimmune diseases." (PMID 23691008, 2013). "Moreover, since the production of IFNα has been described to play a pivotal role in systemic lupus erithemathosus (SLE) as well as in the pathogenesis of other autoimmune disease, we investigated the effect of LAIR-1 cross-linking on pDCs stimulated with DNA/anti-DNA immunocomplexes." (PMID 21151495, 2010). "Although LAIR1 serves as an immune inhibitory receptor and seems non-essential for normal hematopoiesis, it plays a significant role in regulating immune system equilibrium and in protecting against tissue damage caused by hyperactive immune responses or autoimmune disorders." (PMID 38933531, 2024). "In this section, we do not consider the role of LAIR1 molecules in inflammation and/or autoimmune diseases and malaria, but these topics will be of great interest to designing LAIR-targeting therapeutics for these pathological conditions." (PMID 40563506, 2025).
ovarian carcinoma (12 papers, 2018 to 2025). A malignant neoplasm originating from the surface ovarian epithelium. "In those studies, the LAIR-1 expression level was significantly associated with tumor pathological differentiation, in agreement with our previous results for ovarian cancer." (PMID 32628130, 2020). "In summary, we confirm the antitumor activity of LAIR-1 in ovarian cancer cells both in vitro and in vivo, which is associated with the suppression of the PI3K-AKT-mTOR pathway." (PMID 32628130, 2020). "However, previous studies reported that both ELF-1 and LAIR-1 expression were significantly associated with histological grade of ovarian carcinoma, while we overexpressed ELF-1 in HO8910 cells did increase LAIR-1 expression." (PMID 29915163, 2018). "In ovarian cancer, LAIR-1 knockdown increased cell proliferation, migration, invasion and colony formation, and in cervical cancer, LAIR-1 overexpression suppressed cell proliferation and survival." (PMID 40175626, 2025). "LAIR-1 can participate in ovarian cancer cell mitochondrial bioenergy metabolism and OXPHOS, to promote cell proliferation." (PMID 38711526, 2024). "Some research has shown that LAIR‐1 can decrease ovarian cancer cell proliferation and migration via PI3K‐AKT‐mTOR pathway suppression." (PMID 37647449, 2023). "For example, LAIR‐1 overexpression has been detected in oral squamous cell carcinoma, cervical cancer, and ovarian cancer." (PMID 37647449, 2023). "A mouse SKOV3 xenograft model of ovarian cancer was employed to further investigate the in vivo anti-tumorigenic potential of LAIR-1." (PMID 32628130, 2020). "Previous studies have demonstrated the biological function of LAIR-1 in solid tumors, such as ovarian cancer, cervical cancer, and hepatocellular carcinoma." (PMID 32563267, 2020). "The expression of LAIR-1 in ovarian cancer tissues was significantly correlated with tumor grade, and was involved in the proliferation and invasion of HO8910 cells." (PMID 32628130, 2020). "In the present study, we cloned and identified the cDNA sequence of LAIR-1 from the HO8910 ovarian cancer cells." (PMID 32628130, 2020). "In our previous study, we found that LAIR-1 is expressed in ovarian cancer tissues and in several ovarian cancer cell lines, including COC1 and HO8910 cells." (PMID 32628130, 2020). "High expression of LAIR-1 has been reported to be a significant factor in the development of various hematopoietic malignancies, kidney and ovarian cancers." (PMID 33396670, 2020). "Using SKOV3, which is another ovarian cancer cell line expressing lower level of LAIR-1, we confirmed in vitro the effects of LAIR-1 on cell proliferation, colony formation and cell invasion." (PMID 32628130, 2020). "Further analyses of interacting proteins should aid in elucidating the biological functions of LAIR-1 in the progression of ovarian cancer." (PMID 32628130, 2020). "We confirmed this result by using a PI3K inhibitor, LY294002, which can efficiently reverse the effects of LAIR-1 expression in ovarian cancer cells." (PMID 32628130, 2020). "Several studies have reported that LAIR1 is significantly upregulated in multiple types of solid tumors such as ovarian cancer, human cervical cancer, and GBM." (PMID 33147797, 2020). "Up-regulation of LAIR-1 expression in many solid cancers, including cervical and ovarian cancers, has been reported in several studies recently." (PMID 32628130, 2020). "We further studied the effect of these transcription factors on the regulation of LAIR-1 gene expression in ovarian cancer cell HO8910, which we have used in our previous study to investigate the function of LAIR-1." (PMID 29915163, 2018). "We found that LAIR-1 is expressed in epithelial ovarian cancer cells and is involved in cell proliferation and invasion of the ovarian cancer cell line HO8910." (PMID 29915163, 2018).